CD8B2 (CD8B family member 2)
Description:
Identifies cytotoxic/suppressor T-cells that interact with MHC class I bearing targets. CD8 is thought to play a role in the process of T-cell mediated killing (By similarity).
Synonyms: CD8BP
Tractability: Antibody: UniProt places it where antibodies can reach, with medium confidence; UniProt predicts a signal peptide or a membrane-spanning region; its Gene Ontology location is reachable by antibodies, with medium confidence.
Gene: Protein-coding gene on chromosome 2 (106,487,364 to 106,544,297, forward strand). Ensembl gene ENSG00000254126.
Subcellular location: Cell membrane
Gene Ontology:
Molecular function: coreceptor activity; MHC class I protein binding
Biological process: regulation of immune response
Cellular component: plasma membrane
Genetic constraint (gnomAD): Loss-of-function variants: 10 observed, 13.59 expected, observed/expected ratio (o/e) 0.74, 90% interval 0.45 to 1.25. The upper end of that interval is the gene's LOEUF score, 1.25, which puts it in group 5 of 6, group 1 being the genes least tolerant of losing a copy. Missense variants: 182 observed, 216.98 expected, observed/expected ratio (o/e) 0.84, 90% interval 0.74 to 0.95. Synonymous variants: 86 observed, 83.9 expected, observed/expected ratio (o/e) 1.02, 90% interval 0.86 to 1.23.
Homologues: Orthologues: chimpanzee CD8B (96% identical), macaque CD8B (84% identical), dog CD8B (66% identical), pig CD8B (60% identical), guinea pig Cd8b (59% identical), rat Cd8b (53% identical), mouse Cd8b1 (52% identical), zebrafish cd8b (20% identical). Paralogues in human: CD8B (98% identical).
Diseases named in the same sentence as CD8B2 in open-access papers:
CD8B2 is named in the same sentence as 3 diseases in open-access papers, as found by Europe PMC text mining. Sharing a sentence is not in itself a finding about the gene and the disease. The quoted sentences say what the papers report.
Hypertension (1 paper, 2021). The presence of chronic increased pressure in the systemic arterial system. "The SNPs with the highest risk towards hypertension were intergenic SNPs rs1006472 of CD8B2;ST6GAL2, and rs1998081 and rs2424515 of THBD;CD93." (PMID 34575042, 2021).
CD8B2 also shares sentences with these, for which no sentence is quoted: infection (1 paper); tumour (1).